IL5 (interleukin 5)
Diseases named in the same sentence as IL5 in open-access papers (continued):
Sharing a sentence is not in itself a finding about the gene and the disease.
asthma (continued). "In the IL-33-induced asthma model, coadministration of PGE2 or PGE1-alcohol resulted in diminished IL-5 and IL-13 production, reduced eosinophilia and alleviated lung pathology." (PMID 29593738, 2018). "The “Th2-dependent” inflammatory subtype of asthma or CRS is mediated to a large extent by IL-4, IL-5, and IL-13 cytokines." (PMID 29707206, 2018). "Lung resident type 2 innate lymphoid cells (ILC2) have been shown to function as a potential early source for IL-5 and IL-13, and are supposed to contribute to allergen-independent AHR and asthma." (PMID 29678672, 2018). "In the dexa/hypergravity group, IL-4, IL-5 and IL-13 secretion in the BAL fluid decreased statistically significantly (p < 0.001) compared with the asthma group." (PMID 29772010, 2018). "This is in line with the assumption that IL-5 and CCL-11/eotaxin-1 together with others TH2 cytokines play critical roles in orchestrating and amplifying allergic inflammation in asthma." (PMID 29849493, 2018). "Asthma is characterized by an expansion of CD4+ helper T lymphocytes (Th2, Th17), increased production of the Th2 cytokines IL-4, IL-5, and IL-13, an increased level of allergen-specific immunoglobulin E (IgE), eosinophilia and inflammation of the airways." (PMID 30622536, 2018). "The data showed that resveratrol significantly reduced IL-5, IL-13, and TGF-β in the serum and BALF in mice with OVA-induced asthma." (PMID 30619345, 2018). "Although these inhibitors have shown minimal benefits for asthma in clinical trials, knocking-out all of the NOS isoforms decreases airway inflammation and reduces Th2 cytokines such as IL-4, IL-5, and IL-13 in asthmatic mice." (PMID 29302700, 2018). "In fact, ILC2 represents more than half of the IL-5- and IL-13-producing cells in the lungs of mice subjected to ovalbumin (OVA)- or house dust mite (HDM)-induced asthma." (PMID 29593738, 2018). "For this purpose, we determined differential leukocyte counts and concentrations of IFN-γ, IL-5, IL-6, IL-13, and KC/CXCL1 in BALF in a mouse model of OVA-induced asthma." (PMID 29882826, 2018). "Human airway smooth muscle cells, exposed to IL-5, IL-1β and IgE, upregulated expression levels of both stimulatory and inhibitory IL-1 axis molecules, which suggests that modulation of the interleukin-1 axis may potentially also have significant therapeutic implications in the treatment of asthma." (PMID 30380761, 2018). "The CD4+ T cell is a dominant activated T cell subtype in clinical allergic asthma and in animal models of asthma, an mainly contributes to AHR development and allergic inflammation by secreting Th2 cytokines such as IL-4, IL-5, and IL-13." (PMID 29910732, 2018). "Intranasal siRNA nanoparticles targeting c-kit reduced infiltration of eosinophils in BAL fluid, downregulated the production of SCF, IL-4, and IL-5, and suppressed airway mucus secretion in an OVA-induced mouse asthma model." (PMID 28106744, 2017). "Intravenous administration of an IL-5 ASO inhibited airway eosinophilia and antigen-induced late phase AHR, coincident with reduction of IL-5 protein levels in a murine OVA-challenged asthma model." (PMID 28106744, 2017). "Concentrations of IL-4 (23.40 ± 0.78 pg/mL), IL-5 (15.05 ± 1.13 pg/mL), IL-13 (331.93 ± 61.74 pg/ml), IL-17 (72.21 ± 7.10 pg/ml) in BALF of mice in the wild-type group with asthma were significantly higher than that of control group (P < 0.05)." (PMID 28094276, 2017). "In particular, Doganci and colleagues found that local blockade of the sIL-6R in an ovalbumin mouse model of the late-phase asthma response reduced eosinophil numbers in BALF and decreased levels of the Th2 cytokines IL-4, IL-5, and IL-13." (PMID 28334838, 2017). "There was an increase (p<0.01) in the IL-5 levels of the BAL in the (P) and (Asthma) groups when compared with the basal (B) group." (PMID 29145431, 2017).
asthma (continued). "Conversely, in severe asthma with CRS, Th2-derived cytokines of IL-4, IL-5, and IL-13 were markedly expressed in the epithelium, endothelium, subepithelial infiltrating cells, and mucus glands (respectively)." (PMID 28199345, 2017). "Benralizumab targets the receptor for IL-5 (IL-5Rα) and in a phase III study in patients aged 12 years and above with severe uncontrolled asthma, it was well tolerated and depleted blood eosinophils, reduced exacerbation rates, and improved lung function." (PMID 28725641, 2017). "The concentrations of IFN-γ, IL-4, IL-5, IL-10 and IL-17 in BALF were therefore determined, to confirm the establishment of the mouse asthma model at the molecular level." (PMID 28931832, 2017). "Higher expression of Th2-driven cytokines (IL-4, IL-5, IL-9, and IL-13), TSLP, IL-25 and IL-33 in nasal tissues was observed in severe asthma." (PMID 28199345, 2017). "The aim of the present study was to investigate two relevant cytokines, IL-5 and IL-6, FEV1 (% predicted), sickness behaviour and asthma-related quality of life as determinants of self-rated health in patients with asthma." (PMID 28915273, 2017). "Levels of IL-5 in MEE were significantly higher than those in blood in both groups of patients and in OME patients with asthma than in the control group." (PMID 29158869, 2017). "Plasma cytokines (IL-5, IL-6), lung function (FEV1), sickness behaviour, asthma-related quality of life and self-rated health were assessed in 181 patients with allergic asthma aged 18–64 years in a one-year longitudinal study." (PMID 28915273, 2017). "Gene silencing of CD86 by siRNA also decreased airway eosinophilia, BAL fluids IL-5 and IL-13, and CCL17 production, serum OVA-specific IgE levels, and AHR in an OVA-induced mouse asthma model." (PMID 28106744, 2017). "For the analyzes of the IL-4, IL-5 IL-10 and IFN-γ cytokines in the BAL supernatant–the cytokines related to the mechanism (Th2) of asthma were evaluated in the BAL supernatant." (PMID 29145431, 2017). "Daily oral administration of WGP (400 μg) significantly reduced pulmonary eosinophil influx and production of Th2 cytokines (IL-4, IL-5, IL-13), however serum IgE levels were unaffected by WGP treatment in an OVA-induced asthma model." (PMID 27390655, 2016). "Serum IL-31 levels correlated positively with Th2 related cytokines (IL-5, IL-13, and TSLP), asthma severity or total serum immunoglobulin E (IgE), and inversely with asthma control and the forced expiratory volume in 1 second (FEV1)." (PMID 26956917, 2016). "We found that the serum levels of IL-5, IL-13 and TSLP were significantly elevated in patients with asthma compared with controls." (PMID 26956917, 2016). "In this study, in order to investigate the correlation among IL-25, IL-5, IL-13 and nuocyte activities, we used OVA-sensitization and -challenging to induce the mouse model of asthma." (PMID 27617447, 2016). "Pharmacological therapies using specific receptors IL-4, IL-5, TNF and IL-1β blockers are likely to constitute a considerable development in asthma management." (PMID 27536321, 2016). "The serum samples of these mice also had lower IL-1β (all P < 0.05), TNF-α (all P < 0.05), IL-4 (all P < 0.05) and IL-5 (all P < 0.05) levels and higher levels of IFN-γ (P < 0.001) compared with the OVA-induced asthma mouse model." (PMID 27134644, 2016). "Asthma symptoms are related to the presence of activated Th2 cytokine-producing cells (IL4, IL5, IL9 and IL13) in the airway wall." (PMID 26986948, 2016). "Data collected from people with asthma and also in mouse models of asthma driven by inhalation of the model antigen ovalbumin (OVA) have shown that IL-4, IL-5, and IL-13 have potential to serve as an allergic asthma biomarker profile." (PMID 26346739, 2015).
asthma (continued). "By contrast, compared to Neu-Normal asthma, Neu-High asthma had higher IL-8 levels (p<0.01) and lower % predicted FEV1 (p<0.01), but similar levels of eosinophil %, IL-5, IL-13, IL-16, and PDGF-bb and other cytokines and chemokines (data not shown)." (PMID 26011707, 2015). "In addition, ATF3 directly binds to CRE sites in the IL-4, IL-5 and IL-13 promoter regions and ATF3 binding sites were found enriched in a recent epigenomic analysis of regulated genes that play a role for TH2 memory cell differentiation and asthma susceptibility." (PMID 26459392, 2015). "In a previous longitudinal study in 40 children with asthma, exacerbations were predicted by Interleukin 5 (IL-5) in EBC and acidity of EBC (Inflammation Asthma Monitoring, FLAME-study)." (PMID 25799487, 2015). "Subcutaneous injection with perilla seed water/ethanol extract, as a traditional oriental therapeutic herbal acupuncture, seemed to reduce IgE, IL-4, IL-5, and IL-13 in BALF in OVA-induced asthma in mice." (PMID 26064160, 2015). "Instead of the commonly used animal model of asthma induced by OVA, our mouse model showing increased eosinophils and high expression of IL-4, IL-5 and IL-13 detected in BALF and lung tissue is considered to bear a closer resemblance to human asthma." (PMID 24671176, 2014). "Previous studies have revealed that numerous types of inflammatory factors or cytokines play a critical role in classic asthma and CVA, including IL-5, IL-4 and eosinophilic cationic protein." (PMID 25187823, 2014). "Clinical studies have shown an increase in IL-5 in bronchoalveolar lavage fluid (BALF) and bronchial biopsies in asthma, and the level of IL-5 in BALF and the bronchial mucosa correlated with disease severity." (PMID 23544105, 2013). "Mast cells have been shown to play a key role in asthma through their release of a variety of mediators, including histamine, PGD2, tryptase, IL-4 and IL-5." (PMID 23849630, 2013). "An OVA-challenged mouse model of experimental asthma showed that systemic administration of an LXA4 analog blocks AHR, eosinophilic airway inflammation and the production of Th2 cytokines, IL-5 and IL-13." (PMID 23828644, 2013). "IL2, IL4, IL5, IL6, IL13, and TNFαhave been reported to enhance asthma in humans, and Th1 cells have been shown to suppress Th2 cells through the release of IFN-γ." (PMID 23781124, 2013). "Both in vivo and in vitro studies confirmed that Vitamin A and ATRA induce Th2 bias and promote Th2 cytokines realise, such as IL-4, IL-5, IL-13 and GATA-3, which is one of the major characteristics of asthma." (PMID 24204796, 2013). "A number of biological agents have been developed to target cytokines thought to play an important role in asthma pathogenesis, including monoclonal antibody blockers of TNF-α, IL-5, IL-4 and IL-13." (PMID 21896202, 2011). "Asthma is characterized by chronic inflammation in the airways and the presence of a predominance of CD4+ T-helper 2 cells that secrete IL-4, IL-5, and IL-13 cytokines." (PMID 21655126, 2011). "HDM-induced cytokine expression of IL-5, IL-9, IL-10, IL-13, and IFN-γ were significantly elevated in teens with asthma." (PMID 21655126, 2011). "In the mouse model of asthma, the CCL20/CCR6 system plays a pivotal role in allergic airway responses such as airway resistance, airway eosinophilia, and production of IL-5 and IgE." (PMID 22013453, 2011). "Th2 lymphocytes are the key orchestrators of this inflammation, initiating and propagating inflammation through the release of their cytokines, IL-4, IL-5, and TNF-α in turn recruiting and activating eosinophils, the effector cells in asthma." (PMID 20953388, 2011). "While others have demonstrated a decrease in serum concentrations of ECP, IL5, IL8, and TNF-α with montelukast therapy in asthma, allergic rhinitis, and cystic fibrosis, we were unable to show any decrease of these in children with dyspepsia." (PMID 19432972, 2009).
asthma (continued). "The synthesis of many inflammatory mediators such as TNFα, IL-4, IL-5, IL-8, RANTES and eotaxins, thought to be important in asthma pathogenesis, are regulated through activation of p38 MAPK." (PMID 18315837, 2008). "PPARγ agonists also reduce the clinical symptoms in animal models of asthma, a disease which is also thought to be predominantly Th2 type involving IL4, IL5, and IL13." (PMID 17207275, 2007). "In asthma, blood CD4+ T cells express increased mRNA for interleukin (IL)-4, IL-5, and granulocyte macrophage colony stimulating factor, and IL-5 mRNA expression correlates with asthma severity and eosinophilia." (PMID 16393658, 2006). "Unlike T2-high asthma, which benefits from anti-IgE, anti-IL-5, and anti-IL-4Rα biologics, non-T2 asthma lacks effective biologics and is often refractory to corticosteroids." (PMID 41601686, 2026). "Additionally, we explored the correlations between the microbial profiles and inflammatory cytokines known to play key roles in asthma pathogenesis, including IFN-γ, IL-4, IL-5, IL-13, IL-17A, IL-10, and TGF-β1." (PMID 40871265, 2025). "Two studies evaluating 3-year outcomes on anti-IL-5/IL-5Rα therapies found sustained clinical improvements but did not analyze asthma remission." (PMID 40810090, 2025). "In severe asthma, type 2 innate lymphoid cells, which are pivotal in the production of IL4, IL5, and IL13, as well as in T lymphocyte regulation, are markedly increased, along with macrophages, neutrophils, Th1, and Th17 cells, contributing to disease progression." (PMID 40598285, 2025). "The secretion of IL-4, IL-5 and IL-13 cytokines by these cells drives chronic inflammation and excessive immune responses in the airways, thereby further strengthening our understanding of TH2-type immune responses in asthma." (PMID 39980673, 2025). "Consequently, asthma symptoms are exacerbated by the promotion of an increase in CD4+ Th2 cells and the further secretion of cytokines, such as IL-4, IL-5, and IL-13." (PMID 41155294, 2025). "Eosinophilic airway inflammation and high IL-4, IL-5, and IL-13 levels define T2-high asthma, which can be allergic or non-allergic, depending on atopy." (PMID 40486460, 2025). "Th2‐high asthma is characterized by eosinophilic airway inflammation, also known as type 2 inflammation, primarily mediated by Th2 and ILC2 cells and involving pathways such as IL‐4/IL‐13, IL‐5, and IL‐25/IL‐33/TSLP." (PMID 41310922, 2025). "Therapeutic strategies for non-asthma T2 conditions may target shared molecular pathways, including JAK–STAT signaling and IL-5-mediated eosinophil activation, to improve disease control and reduce recurrence." (PMID 40508151, 2025). "To further validate the role of eosinophils in the asthma‐induced TMJOA alleviation, we depleted these cells using an anti‐IL‐5 antibody (TRFK5) and observed changes in the synovium, cartilage, and subchondral bone, while Sham rats received an irrelevant immunoglobulin G (IgG) control." (PMID 40125663, 2025). "In a study of the Danish asthma registry, decreasing Feno was found to be a predictor for remission in a cohort receiving anti-IL5/IL-5Rα therapy; however, decreasing Feno was not a predictor of remission in our cohort." (PMID 40810090, 2025). "Although MMP-9 has been extensively linked to asthma severity, as its levels in sputum and lung tissue correlate with disease severity, our study did not observe changes in MMP-9 following IL-5 stimulation." (PMID 41188935, 2025). "These cytokines activate ILC2s producing large amounts of T2 cytokines predominately IL-5 and IL-13, leading to AD when meeting again allergens, and can promote the occurrence of asthma independent of adaptive immunity." (PMID 40236701, 2025). "Additionally, glucocorticoids inhibit ILC2 function by suppressing IL-5, IL-13, and IL-9 production via MEK/JAK-STAT signaling pathways, as demonstrated in studies using ILC2s sorted from asthma patients’ PBMCs." (PMID 40355861, 2025).
asthma (continued). "Major cytokines involved in asthma include IL4, IL5, and IL13 derived from CD4+ T cells type II." (PMID 40468357, 2025). "This umbrella review indicated that anti-IgE treatment, anti-IL5/5Rα treatment, anti-IL4Rα treatment, and anti-TSLP treatment may be beneficial to patients with severe asthma." (PMID 40520782, 2025). "Specifically, butyrate alleviates asthma by suppressing GATA3 expression and reducing IL-5 and IL-13 secretion from ILC2s, whereas propionate acts through free fatty acid receptor 3 to promote DC and macrophage differentiation, attenuating allergic inflammation." (PMID 41229685, 2025). "In summary, we report the first large real‐world analysis of tezepelumab effectiveness and clinical remission in severe asthma and in particular in patients who have failed to respond adequately to anti‐IL5/5R therapy." (PMID 40365686, 2025). "Furthermore, ITIH4 also suppressed IL-5 and IL-13 levels in the intestinal tissues of OVA-induced asthma mice (p < 0.05), suggesting a systemic immunomodulatory effect that extends beyond the lungs." (PMID 40410722, 2025). "Our analysis represents the first report of tezepelumab effectiveness in patients with severe asthma who have failed to adequately respond to other biologic therapies, in particular those targeting the IL5‐eosinophil pathway." (PMID 40365686, 2025). "In asthma patients infected with RV, IL-5 inhibits the function of pDCs and the expression of TLR7 by promoting the maturation and survival of eosinophils, thereby suppressing the antiviral response and leading to the exacerbation of asthma." (PMID 40636260, 2025). "Biologic therapies target type 2 inflammatory mediators, such as immunoglobulin E (IgE), interleukin-4 (IL-4) and interleukin-5 (IL-5), and thymic stromal lymphopoietin (TSLP), thereby reducing asthma exacerbations and OCS use while improving QOL and lung function." (PMID 40861628, 2025). "Indeed, when used as an add-on strategy in patients with mild to moderate asthma, subcutaneous AIT (SCIT) helps reduce the use of inhaled β2 agonists and decreases type 2 cytokine release (IL5 and IL-13) by PBMCs." (PMID 41145900, 2025). "Except for tezepelumab (anti-TSLP), these biologics are approved for asthma with specific biomarker elevations relevant to these pathways: sensitization to a perennial aeroallergen (anti-IgE), elevated AEC [anti-IL-5, anti-IL-5 receptor (IL-5R), anti-IL-4Rα], and increased FeNO (anti-IL-4Rα)." (PMID 39586024, 2025). "Positive correlations between blood eosinophils counts and FeNO levels, observed in all cohorts of asthmatics but not in healthy controls, illustrates the dysregulation of IL-5 in asthma and the relevance of this pathway in asthma therapy." (PMID 40943268, 2025). "Although the investigation using human isolated LPS-stimulated eosinophils did not demonstrate a reduction in IL-5, the obese asthma mouse model exhibited a decrease in IL-5 levels in bronchoalveolar lavage." (PMID 39768911, 2024). "There are some diversified explanations for why anti-IL-5 therapy does not occur as efficiently in AD as for asthma treatment." (PMID 39062104, 2024). "Biologics targeting IgE, IL-5, IL-4/IL-13, and TSLP are crucial in severe asthma treatment." (PMID 38525773, 2024). "While a four-week treatment with symbiotics (prebiotics and probiotics) did not alter bronchial inflammation in human patients with asthma, significant decreases in the systemic production of T2-cytokines such as IL-5 were observed in one study." (PMID 38254421, 2024). "Additionally, compared to the Asthma + Vehicle group, the IDF-11,774 group exhibited a significant decrease in IL-4, IL-5, IL-13, and IgE." (PMID 39061007, 2024). "The expression levels of FCER1A and TLR‐9 in IL‐5‐ or IL‐17‐activated eosinophils and those of aryl hydrocarbon receptor and TLR‐7 in IL‐5‐activated eosinophils were significantly higher for patients with asthma than for normal individuals." (PMID 39575691, 2024).